PINK1 (PTEN induced kinase 1)
Diseases named in the same sentence as PINK1 in open-access papers (continued):
Sharing a sentence is not in itself a finding about the gene and the disease.
hyperthyroidism (2 papers, 2022 to 2023). Overactivity of the thyroid gland resulting in overproduction of thyroid hormone and increased metabolic rate. "Rats with hyperthyroidism had significant decreases in PINK1 and Parkin levels by two and four times, respectively." (PMID 36430802, 2022). "In rats with hyperthyroidism, the PINK1 and Parkin levels decreased 1.9-fold." (PMID 36766738, 2023).
Infertility (2 papers, 2024 to 2025). "Knockout of PINK1 in Drosophila leads to infertility and mitochondrial dysfunction, which can be alleviated by overexpression of Parkin." (PMID 38200521, 2024). "Moreover, in the KEGG and RCTM pathways, autophagy, PINK1-PARKIN-mediated mitophagy, and NF-κB signaling dominated, with PD-1 checkpoint pathways as well as other significant pathways and their overlap genes suggesting immune–infertility crosstalk." (PMID 41227338, 2025).
intracerebral hemorrhage (2 papers, 2024 to 2025). A cerebrovascular disorder characterized by bleeding into one or both cerebral hemispheres including the basal ganglia and the cerebral cortex. "Reportedly, PINK1 mRNA expressions were markedly upregulated in the cerebral tissues of patients with intracerebral hemorrhage." (PMID 40979207, 2025). "Alternatively, brain PINK1 mRNA expressions were substantially up-regulated in patients with intracerebral hemorrhage, and the increased levels were strongly correlated with hemorrhagic amount." (PMID 40979207, 2025). "While the role of Pink1 in intracerebral hemorrhage (ICH)-related neurological deficits and inflammatory responses is not deciphered." (PMID 38266580, 2024). "Also, there was a substantial elevation of brain PINK1 mRNA expressions in patients with intracerebral hemorrhage." (PMID 40979207, 2025).
kidney stone (2 papers, 2024 to 2025). "This study aims to uncover the molecular mechanisms underlying pediatric kidney stone formation induced by renal calcium deposition by utilizing high-throughput sequencing data to reveal the regulation of PINK1 by MyoD1." (PMID 39242558, 2024). "The results indicate that overexpression of PINK1 can reverse the downregulation of PINK1 and the kidney stone-related protein OPN caused by knockdown of MyoD1." (PMID 39242558, 2024). "The results above indicate that the loss of PINK1 can effectively improve the phenotype of kidney stones." (PMID 39242558, 2024). "Our research shows that PINK1 plays an essential role in the formation of pediatric kidney stones, possibly by regulating mitochondrial homeostasis to alleviate cellular damage caused by crystal stones." (PMID 39242558, 2024). "Through experimental verification, we will reveal how MyoD1 activates the transcription of PINK1, thereby impacting mitochondrial oxidative stress and promoting the occurrence of kidney stones." (PMID 39242558, 2024). "The results indicate that during the process of kidney stone formation, PINK1, as a downstream molecule of MyoD1, can enhance mitochondrial autophagy, thereby promoting cell apoptosis and accelerating the progression of kidney stones." (PMID 39242558, 2024). "We found that PINK1 is highly expressed in pediatric nephrolithiasis patients, consistent with some earlier research findings that revealed abnormal expression of PINK1 in various diseases." (PMID 39242558, 2024). "By incorporating the studies of MyoD1 and PINK1 into the field of kidney stones, this research provides a new perspective for understanding the pathogenesis of kidney stones." (PMID 39242558, 2024). "This study provides insights into the potential roles of MyoD1 and PINK1 in pediatric nephrolithiasis, offering a novel perspective for understanding the pathogenesis of this disease." (PMID 39242558, 2024). "Bioinformatics analysis revealed that the PINK1 gene is upregulated and vital in pediatric kidney stone patients." (PMID 39242558, 2024). "This study explores the molecular mechanism of MyoD1-mediated mitochondrial homeostasis regulation in the induction of pediatric kidney stone formation through the transcriptional activation of PINK1 expression." (PMID 39242558, 2024). "The results demonstrate that under the successful establishment of the kidney stone model, sh-MyoD1 and Ad-PINK1 exhibit highly desirable knockdown and overexpression efficiencies." (PMID 39242558, 2024). "To elucidate the impact of PINK1 on pediatric nephrolithiasis, we utilized RNAi technology to silence PINK1 in COM-induced HK-2 cell line, a model for calcium oxalate monohydrate kidney stones." (PMID 39242558, 2024). "The correlation analysis results indicate a strong positive correlation between the expression of MyoD1 and PINK1, and they both show an upregulation trend in pediatric kidney stones." (PMID 39242558, 2024). "We identified MyoD1 as an upstream transcription factor of PINK1 that contributes to the occurrence of pediatric kidney stones through the activation of PINK1." (PMID 39242558, 2024). "In the future, we will further investigate the dynamic expression and function of MyoD1 and PINK1 in pediatric nephrolithiasis, aiming to reveal their more detailed molecular mechanisms in the disease progression." (PMID 39242558, 2024). "Although the functions of MyoD1 and PINK1 have been extensively studied in other diseases, their roles in pediatric kidney stones still need to be clarified." (PMID 39242558, 2024). "Furthermore, targeting AMPK/PINK1/Parkin-mediated mitophagy has been shown to reduce ferroptosis both in vitro and in vivo, offering protective effects against kidney stone formation." (PMID 40629421, 2025). "Although it is known that MyoD1 could regulate the expression of many genes, this is the first time that it has been found to activate the expression of PINK1 and affect the formation of pediatric kidney stones." (PMID 39242558, 2024).
kidney stone (continued). "We found that silencing MyoD1 could inhibit the formation of kidney stones by downregulating PINK1 expression in both in vitro and in vivo kidney stone models, providing new insights into the pathogenesis of pediatric nephrolithiasis." (PMID 39242558, 2024). "At the same time, we will validate our findings in a larger clinical sample to evaluate whether MyoD1 and PINK1 could serve as potential targets for treating pediatric kidney stones." (PMID 39242558, 2024). "Through experimental verification, we found that the silence of PINK1 could inhibit the formation of kidney stones inside and outside the body, indicating that PINK1 plays an essential role in the formation process of pediatric kidney stones." (PMID 39242558, 2024). "Our in vivo and in vitro experiments confirm that silencing MyoD1 could inhibit mitochondrial oxidative stress and kidney stone formation in rats by downregulating the expression of PINK1." (PMID 39242558, 2024). "In summary, this study preliminarily concludes the following: MyoD1 may promote the occurrence and development of kidney stones through transcriptional activation of PINK1 expression, which in turn promotes mitochondrial oxidative stress." (PMID 39242558, 2024). "This study utilized a rat model of kidney stones to confirm the inhibitory effect of silencing MyoD1 on PINK1 expression, which could regulate mitochondrial oxidative stress and impact kidney stone formation." (PMID 39242558, 2024). "However, there are currently no conclusive research results regarding the specific role of PINK1 in pediatric kidney stones." (PMID 39242558, 2024). "This study reveals for the first time that MyoD1 may regulate mitochondrial homeostasis and induce pediatric kidney stone formation by transcriptionally activating the expression of PINK1, shedding light on the possible mechanism behind it." (PMID 39242558, 2024). "Our in vitro and in vivo experiments demonstrated that silencing PINK1 could inhibit kidney stone formation by suppressing mitochondrial oxidative stress both in vitro and in vivo." (PMID 39242558, 2024). "In this study, we discovered that MyoD1 may promote kidney stone formation and development in pediatric patients by transcriptionally activating PINK1 to induce mitochondrial oxidative stress." (PMID 39242558, 2024). "Another important finding of this study is that MyoD1 is an upstream transcription factor of PINK1, which could participate in developing pediatric kidney stones by activating PINK1." (PMID 39242558, 2024). "It is hypothesized that MyoD1 could affect the occurrence of kidney stones by activating the transcription of PINK1." (PMID 39242558, 2024). "Finally, we will also attempt to develop drugs that could suppress the expression of MyoD1 or PINK1, providing new strategies for treating pediatric kidney stones." (PMID 39242558, 2024). "Our in vivo and in vitro experiments collectively confirmed that silencing MyoD1 could inhibit mitochondrial oxidative stress, mitochondrial autophagy, and cellular apoptosis in a rat model of kidney stones by downregulating PINK1 expression, consequently suppressing the formation of kidney stones." (PMID 39242558, 2024). "In addition, our findings also provide potential targets for developing new strategies to treat pediatric kidney stones, such as developing drugs that could inhibit the expression of MyoD1 or PINK1." (PMID 39242558, 2024). "The results indicate that the absence of MyoD1 and PINK1 is of significant importance for maintaining the integrity of mitochondrial membrane structure during the process of kidney stone formation." (PMID 39242558, 2024). "However, we do not know the role of PINK1 in pediatric kidney stones." (PMID 39242558, 2024).
liver disease (2 papers, 2021 to 2022). "PINK1 dysfunction leads to mitochondrial dysfunction and subsequent disease development, including PD, cancer, liver disease, heart disease, and skeletal muscle injury." (PMID 34751247, 2021). "Recent studies suggest that PINK1 may also have a protective role in multiple liver diseases, including alcoholic liver disease, nonalcoholic steatohepatitis (NASH), and acetaminophen (APAP)-induced liver injury (AILI)." (PMID 35461334, 2022). "However, the involvement and regulation of PINK1 in the pathogenesis of liver diseases remain poorly understood, especially in ACLF." (PMID 35461334, 2022).
Lung Disease (2 papers, 2019 to 2022). "In pulmonary disorders, PINK1 was reported to attenuate mtDNA release in alveolar epithelial cells." (PMID 35223833, 2022). "To investigate the link between PINK1 levels, cell-free mtDNA and ILD, we obtained plasma and bronchoalveolar lavage (BAL) samples from a cohort of patients from the Interstitial Lung Disease Clinic of the National Institute of Respiratory Diseases in Mexico City." (PMID 31170232, 2019).
lymph node metastasis (2 papers, 2023). "Cox univariate and multivariate analyses were performed to determine the risk factors affecting the OS of patients with ESCC, including sex, age, location, tumor size, grade, T stage, lymph node metastasis, metastasis, TNM stage, and PINK1 and PARK2 expression patterns." (PMID 37833780, 2023). "Our findings indicated that PINK1 protein expression was associated with the grade, T stage, and TNM stage but not with age, sex, location, tumor size, lymph node metastasis, or metastasis." (PMID 37833780, 2023).
malnutrition (2 papers, 2021 to 2024). Inadequate nutrition resulting from poor diet, malabsorption, or abnormal nutrient distribution. "Future studies should be performed to determine the downstream factors of PGC‐1α and PINK1 or other pathways of mitochondrial homeostasis in malnutrition." (PMID 33650806, 2021). "The expression levels of PGC‐1α and PINK1 protein were significantly lower in both the plantaris and soleus muscles of the malnutrition group than those in the control group." (PMID 33650806, 2021). "However, the level of PINK1 protein expression decreased despite increased oxidative stress due to malnutrition in the present study." (PMID 33650806, 2021). "The effect of malnutrition on autophagic machinery and mitochondrial quality control in LPS-challenged BM neutrophils, where we found higher PINK1 and lower ATG5 and p62, remains to be explored further and may independently drive neutrophil activation and pathology." (PMID 39028622, 2024). "Together our results indicate that malnutrition‐induced downregulation of SIRT1 impairs mitochondrial homeostasis and metabolic capacity in skeletal muscle through decreased PGC‐1α and PINK1." (PMID 33650806, 2021).
mastitis (2 papers, 2021 to 2026). Inflammation of breast tissue during lactation or postpartum due to an obstructed duct or infection. "Our study for the first time showed that mitophagy mediated by PINK1/Parkin was inhibited in E. coli-induced mastitis." (PMID 34594329, 2021). "This study elucidates the protective role of mitophagy mediated by PINK1/Parkin under E. coli-induced mastitis in MAC-T cells using 3-MA and Rapa." (PMID 34594329, 2021).
muscular dystrophy (2 papers, 2023 to 2025). Muscular dystrophy (MD) refers to a group of more than 30 genetic diseases characterized by progressive weakness and degeneration of the skeletal muscles that control movement. "Recent studies show that UA initiates mitophagy via stabilizing PINK1 and activates autophagy, thereby prolonging lifespan in normal C. elegans and improving muscle function in C. elegans and rodents with muscular dystrophy." (PMID 37828862, 2023).
nasal polyps (2 papers, 2022 to 2025). "Western blot analysis of mitochondrial proteins also revealed significantly reduced levels of PINK1, parkin, BNIP3, and FUNDC1 in the nasal polyps of patients with eCRSwNP (P < 0.001, 0.004, 0.002, and 0.013, respectively), compared with control tissues." (PMID 35747690, 2022). "Beclin 1, PINK1, BNIP3, and FUNDC1 levels were significantly reduced in the nasal polyps of patients with eCRSwNP or noeCRSwNP." (PMID 35747690, 2022). "In this study, we demonstrated that the expression of PINK1, parkin, BNIP3, and FUNDC1 proteins was markedly decreased in the nasal polyps of patients with eCRSwNP, compared with control tissues." (PMID 35747690, 2022). "The expression of PINK1, BNIP3, and FUNDC1 proteins was also decreased in the nasal polyps of patients with noeCRSwNP." (PMID 35747690, 2022). "Western blot analysis of total proteins revealed reduced levels of PINK1, parkin, BNIP3, and FUNDC1 in the nasal polyps of patients with eCRSwNP (P = 0.002, <0.001, 0.001, and <0.001, respectively) or noeCRSwNP (P = 0.002, <0.001, <0.001, and <0.001, respectively), compared with control tissues." (PMID 35747690, 2022).
ovarian tumor (2 papers, 2013 to 2023). "In this paper, we identified PINK1 from autophagy-related kinases as the most closely associated kinase with poor prognosis of ovarian tumor." (PMID 37940999, 2023). "Collectively, these observations demonstrate that PINK1 is closely associated with poor prognosis in ovarian tumor." (PMID 37940999, 2023). "To explore the role of PINK1 in the development of ovarian tumor, we checked the expression levels of PINK1 in several cell lines including A2780, ES-2, SKOV3, OVCAR3 cancer cells, and ovarian epithelial cell line IOSE80." (PMID 37940999, 2023). "The PINK1 (PARK6) gene was first described as PTEN-induced putative kinase 1, a ubiquitous gene product whose expression was abolished in ovarian tumor tissues due to defect in PTEN signaling." (PMID 23626584, 2013).
pancreatic ductal adenocarcinoma (2 papers, 2020 to 2023). An infiltrating adenocarcinoma that arises from the epithelial cells of the pancreas. "Interestingly, we identified PINK1 as a good prognostic factor in PDAC (pancreatic ductal adenocarcinoma) (OS: log rank P = 0.03)." (PMID 33244455, 2020). "In Kras-driven pancreatic ductal adenocarcinoma (PDAC), the deletion of PINK1 and PARK2 increased cell proliferation and metastasis." (PMID 37833780, 2023).
papillary renal cell carcinoma (2 papers, 2020 to 2022). A rare subtype of renal cell carcinoma, arising from the renal tubular epithelium and showing a papillary growth pattern, which typically manifests with hematuria, flank pain, palpable abdominal mass or nonspecific symptoms, such as fatigue, weight loss or fever. "The aim of this study was to investigate the mitophagy-related genes PINK1 and PARK2 in papillary renal cell carcinoma and their association with prognosis." (PMID 33139776, 2020). "The downregulation of PINK1 is a strong predictor of poor survival in papillary renal cell carcinoma." (PMID 33139776, 2020). "PINK1 and PARK2 were significantly downregulated in papillary renal cell carcinoma at transcript and protein levels." (PMID 33139776, 2020). "The ubiquitin-dependent PINK1/Parkin pathway is the most common mitophagy cascade, and some core genes within this pathway, such as PINK1 and PARK2, can predict prognosis in patients with papillary renal cell cancer." (PMID 36304466, 2022). "In silico data of PINK1 and PARK2 were analyzed in TCGA cohorts of papillary renal cell carcinoma comprising 290 tumors and 33 corresponding non-neoplastic renal tissues." (PMID 33139776, 2020).
periodontal disease (2 papers, 2024 to 2025). "In this study, we demonstrated that PINK1 controls inappropriate formation of osteoclasts that is frequently found in periodontal diseases." (PMID 38181706, 2024). "Here, we delineated the mechanism by which PINK1 regulates osteoclast formation and bone resorption and we suggest that maintaining proper mitochondrial homeostasis in osteoclasts can be considered as a therapeutic strategy for periodontal diseases." (PMID 38181706, 2024).
rheumatoid arthritis (2 papers, 2022 to 2023). A chronic, systemic autoimmune disorder characterized by inflammation in the synovial membranes and articular surfaces. "Taken together, these findings suggest that inhibiting mitophagy by decreasing PINK1 gene expression and/or protein stabilization in RASFs is a new putative therapeutic modality for rheumatoid arthritis." (PMID 35628458, 2022). "Although loss-of-function PINK1 mutations are a major contributing factor to familial Parkinson’s disease, increased PINK1 protein aggregation appears to exacerbate rheumatoid arthritis, contributing to joint destruction." (PMID 35628458, 2022). "We demonstrated that in RASFs, which contribute to joint breakdown in rheumatoid arthritis, PINK1 knockdown decreased cell invasion and migration, including under TNF-α stimulation." (PMID 35628458, 2022). "In addition, macrophages from rheumatoid arthritis (RA) patients expressed tumor necrosis factor (TNF), which inhibited PTEN-induced putative kinase 1 (PINK1)-mediated mitophagy and altered mitochondrial function to elevate cytosolic mtDNA levels." (PMID 38036728, 2023).
silicosis (2 papers, 2025). Silicosis is a respiratory disease caused by breathing in (inhaling) silica dust. "Western blot analysis showed a stronger activation of Pink1 in H2 group compared to both the silicosis group and the Tet group." (PMID 41561355, 2025). "We found that silencing Alcat1 did not affect PINK1 expression in the mitochondria of Pla2g7-overexpressing macrophages, indicating that CL-related mitochondrial autophagy pathways are influenced by Lp-PLA2 levels in silicosis, via PINK1/Parkin-dependent and PINK1/Parkin-independent pathways." (PMID 40389600, 2025). "Western blot analysis indicated that the mitophagy marker Pink1 (p = 0.049, 95%CI = 0.00–0.55) and Parkin (p = 0.031, 95%CI = 0.04–0.51) were decreased in the silicosis group, while p62 (p = 0.048, 95%CI = −0.21 to 0.00) was upregulated, suggesting that autophagic flow was inhibited." (PMID 41561355, 2025).
sporadic amyotrophic lateral sclerosis (2 papers, 2018 to 2021). Sporadic amyotrophic lateral sclerosis is a amyotrophic lateral sclerosis in which there is no known cause, such as no family history. "Pink1, a gene that causes PD when mutated, is also strongly associated, as it is Sqtsm1, a gene involved in sporadic amyotrophic lateral sclerosis pathology." (PMID 29906661, 2018).